TNF (tumor necrosis factor)
Diseases named in the same sentence as TNF in open-access papers (continued):
Sharing a sentence is not in itself a finding about the gene and the disease.
leukemia (continued). "It has been reported that TNF can be produced by various leukemia cells, including AML, ALL, CML, CLL, and so on." (PMID 33109189, 2020). "A research study offered proof of the effect of the tumor necrosis factor G/A (TNFG/A) genotype and A alleles on the propensity for leukemia, since a correlation of LT-alphaG/G genotype with CLL was described." (PMID 32102441, 2020). "High TNF-α concentrations are suggestive of aggressive leukemia, thus suggesting an action in B-CLL evolution." (PMID 32102441, 2020). "In comparison to mock and CEA control CAR T cells, CSPG4-CAR T cells secreted significantly more TNF upon co-culture with KOPN8 leukemia cells." (PMID 31195686, 2019). "Macrophage depletion sensitized leukemia cells to apoptosis via induction of TNF-α signaling, and leukemia cells were killed through a TNF-α-dependent mechanism." (PMID 31370273, 2019). "Consistently, PK6 blocked TNF-induced necroptosis in human leukemia U937 cells with an EC50 of ~1.33 μM." (PMID 31235688, 2019). "Indeed, TNF blockade prevented acute GvHD in most mouse models but may also affect graft-vs.-leukemia activity as transplantation of TNFR1 deficient donor CD8 T cells resulted in an increased leukemia relapse after allo-HCT." (PMID 31555271, 2019). "The mechanisms underlying GVL are of interest, as both T cells, natural killer (NK) cells, and cytokines, such as IFN-γ and tumor necrosis factor-α, possess anti-leukemia activity." (PMID 30619371, 2018). "For the remaining three diseases, Leukemia (Lymphoid), Leukemia (Myeloid, Acute) and Adenocarcinoma, we find at least one of their casual genes have strong connections with TNF in PPI network." (PMID 30713550, 2018). "P. yoelii infection enhanced T and B cell proliferation and increased the levels of the Th1 IFN-γ and TNF-α, suggesting that adaptive immunity is involved in the anti-leukaemia effect." (PMID 29764519, 2018). "Recent studies have shown that guggulsterone isolated from Commiphora muku were able to block the activation of NF-κB in TNF-α induced epithelial and leukemia cells." (PMID 30245627, 2018). "A treatment sensitizes human leukemia U937 cells to TNF-α-induced apoptosis through the suppression of nuclear factor-κB and reactive oxygen species." (PMID 28923043, 2017). "Previous studies have shown that exogenous HMGB1 of levels reach as high as 200 ng/ml during anti-neoplastic immunity of leukemia chemotherapy and induce TNF-α and IL-1β secretion." (PMID 28404891, 2017). "In both cell lines investigated, PsA-D incubation was able to induce a significant blockade of cytokine secretion: In THP-1 monocytic leukemia cells pseudopterosin reduced TNFα release by at least 47%, blocked IL-6 release by 50% and MCP-1 release by 73%." (PMID 28832545, 2017). "For instance, the combined treatment of mice with TNF and leukemia inhibitory factor results in a significantly increased protective effect against a (generally lethal) LPS dose when compared to TNF application alone." (PMID 29250561, 2017). "This set of experiments demonstrates that Sorafenib interferes with the assembly of the necrosome during BV6/TNFα-induced necroptosis in leukemia cells." (PMID 28978109, 2017). "Differentiated human promyelocytic leukemia cells (dHL-60 cells) and human umbilical vein endothelial cells (HUVECs) were activated by treating them with TNF-α (10 U/ml) for 12 hrs." (PMID 28220827, 2017). "In leukemia cells, celastrol inhibited pro-survival NF-κB signaling and enhanced TNFα-mediated apoptosis." (PMID 29190976, 2017). "Consistent with this view, both TNFα and Fas ligand have been shown to induce rRNA degradation in human leukemia cells." (PMID 26911141, 2016). "The previous study reported that transmembrane TNF-α was highly expressed in chemoresistant leukemia cells, and inhibiting transmembrane TNF-α reversed chemoresistance." (PMID 27835602, 2016).
leukemia (continued). "In particular, leukemia blasts of patients with AML show higher TNF-α production than do the corresponding cells in healthy individuals." (PMID 26516703, 2015). "A previous study demonstrated that SFN triggers TNF-á-induced apoptosis through inhibition of NFκB and activation of caspase-3 in leukemia cells." (PMID 27625902, 2015). "For instance, it has been shown that α5β1 integrin upregulated the resistance to TNF induced apoptosis in adherent leukemia cells." (PMID 24860788, 2014). "Autophagic cell death is also induced by many other stimuli, such as platonin-treated leukemia cells, TNFα-treated cells, and death receptor-mediated cell death in cells lacking FADD, caspase activation, or NF-κB activation." (PMID 24947784, 2014). "Concerning the possible targets of resveratrol analogs, an inhibition of the TNF alpha-induced activation NFkB by polyhydroxylated resveratrol derivatives i.e., the hexahydroxystilbene in leukemia HL60 cells has been reported." (PMID 24962390, 2014). "Next we utilized the U937 human hystiocytic leukemia cell line, which is known to undergo apoptosis upon treatment with TNF-α in the presence of cycloheximide (CHX), but necrosis in the additional presence of Z-VAD-fmk, a pan-caspase inhibitor." (PMID 24312463, 2013). "Together these findings support the role of TNF-α in GB induced cell death of leukemia/lymphoma cells." (PMID 24039967, 2013). "Prior to our work, supernatants of FD leukemia samples containing IL-6 and IL-10, TNF-α, and IL-1β were shown to trigger a block in DC differentiation in vitro." (PMID 23616009, 2013). "We found that TNF-α activated ECs indeed facilitated adhesion of both KG-1 and HL-60 leukemia cells." (PMID 23560111, 2013). "Correlating with the increased monocyte viability, the leukemia supernatant (1:3 dilution) induced the secretion of IL-10, TNF-α, IL-6, and IL-1β in both experiments." (PMID 23616009, 2013). "The role of tumor necrosis factor (TNF) and TNF-receptor superfamily members in the pathophysiology of leukemia has recently been documented." (PMID 24427158, 2013). "Smac mimetic BV6 enhanced TNF-induced cell death in leukemia cells in 2 different ways: necroptosis, when the cells were apoptosis resistant (FADD– and caspase-8–deficient), and caspase-8–dependent apoptosis in apoptosis-proficient cells." (PMID 22929310, 2012). "The cells were then transfected with mRNA from the leukemia cell line Jurkat E6 by electroporation and incubated for additional 24 h or 2 days in the presence of pro-inflammatory cytokines (TNFα, IL-1β, IL-6 and PGE2) to obtain mature DCs." (PMID 17608923, 2007). "Groups of mice with leukaemia L1210 and P388 receiving 2-CdA combined with TNFα had shorter survival times than animals treated with these agents separately." (PMID 18475640, 1995). "Moreover, we report that leukemia-derived proinflammatory cytokines, TNF-α, IL-27, and IFN-γ, induced CXCL10 in the meningeal stroma." (PMID 41129238, 2026). "These instances may raise concerns about the potential of anti-TNF medications to exacerbate leukemia." (PMID 39949431, 2025). "The analysis of all batches of anti-leukemia CTLs produced so far documented that the majority of effector cells were CD3+/CD8+ cells, with a memory/terminal activated phenotype displaying efficient capacity to lyse patients’ LB and to secrete IFNγ and TNFα in response to leukemia cells." (PMID 40547030, 2025). "Research has demonstrated that TNF-α plays a crucial role in the direct lysis of carcinoma cells in leukemia cell lines and enhances the anti-tumor effects of various chemotherapy drugs on leukemia and lymphoma cell lines." (PMID 39830670, 2024). "In addition, MSCs interfered with the secretory potential of leukemia-associated WT1- and ROR1-targeting CTL clones, inhibiting the release of IFNγ, tumor necrosis factor alpha, and IL-2." (PMID 38231344, 2024).
leukemia (continued). "In 1992, an exogenous ribozyme directed against the mRNA of the tumor necrosis factor α (TNFα) was delivered using lipofectin (DOTMA-DOPE mix) for cationic-liposome-mediated transfection into human promyelocytic leukemia cells (HL60) and peripheral blood mononuclear cells." (PMID 36986734, 2023). "In addition, inhibition of p38/MK2 facilitates ripoptosome assembly and autocrine TNF production in myeloid cells induced by smac mimetics (SM), and has been suggested as a strategy to overcome SM-resistance in leukemia." (PMID 37495567, 2023). "A number of chemists have synthesized small compounds to inhibit leukemia by targeting TNFα." (PMID 37371757, 2023). "The exosomes of AML origin and MSC origin may play a role in MDS leukemia transformation via targeting TNF-α/ROS-Caspase3 pathway." (PMID 37382733, 2023). "In leukemia cells grown in vitro, treatment with HB evidently induces the TNFα regulated pro‐apoptotic cascade, whilst in PBMC a pro‐inflammatory process is induced with notable association of anti‐apoptotic factors (c‐FLIP, caspase‐8 and ‐10), which forms the apoptosis inhibitory complex (AIC)." (PMID 36369656, 2023). "In addition, in several clinical observations, the TNF-α expression levels positively correlated with adverse clinical endpoints in leukemia." (PMID 35897788, 2022). "In the leukemia group, TNF concentration was higher in the post-index group, compared with those in the pre-index group (p < 0.05), and IL-10 concentration was significantly higher in the post-index group of the head and neck carcinoma group, compared to the pre-index group (p < 0.05)." (PMID 35476641, 2022). "Reduced IL-6 and TNF-α in LPS activated human leukemia monocytic cell line (THP-1) cells." (PMID 35744969, 2022). "In peritoneal macrophage and leukemia cell models, ginseng polysaccharide (GPS) stimulated macrophages to increase the levels of cytokines, including tumor necrosis factor-α (TNF-α), interleukin-1 (IL-1), IL-6, and nitric oxide (NO) production against leukemia." (PMID 34443587, 2021). "When the leukemia cell line HL-60 was added to the membrane-seeded iPSC-ECs and hCBECs, a significantly higher number of HL-60 cells adhered after activation of the EC monolayers with TNFα." (PMID 34442603, 2021). "This led us to hypothesize that TNFα induces vascular changes during leukemia growth partly via miR-126 downregulation." (PMID 34372909, 2021). "However, it was shown that marizomib potentiates cell death induction upon activation of TNF-receptors by TNFα in leukemia and multiple myeloma cells." (PMID 34168123, 2021). "These skewed NK cells secrete IL-17, GM-CSF, TNFα, which could favor the growth of leukemia by acting directly on malignant cells." (PMID 34804065, 2021). "TNFα was shown to play a major role in leukemia control after allo-HCT36." (PMID 34750374, 2021). "In leukemia patients, IL6 produced by adult T-cell leukemia/lymphoma cells may cause fever and further activate macrophages to secrete TNF-α, leading to shock and exacerbation of the fever." (PMID 32110485, 2020). "In addition to upregulating MHC II and costimulatory molecules, TGF-β1-silenced leukemia cell-derived exosomes promote DC function by inducing the secretion of interleukin (IL)-12p70 and tumor necrosis factor (TNF)-α." (PMID 33183286, 2020). "There was also evidence showing that TNF induced MMP9 expression or secretion in leukemia cells." (PMID 33109189, 2020). "BPA treatment in cell culture of a monocyte-like cell line derived from a leukemia patient and human peripheral blood macrophages have been found to release the proinflammatory cytokines TNFα and IL-6 and to decrease the anti-inflammatory/ regulatory cytokines IL-10 and TGFβ." (PMID 31551929, 2019). "However, Mattijssen and Maraia found that LARP4B participated in the regulation of TNF-alpha-TTP as its functional activity in MLL-AF9 leukemia stem cells." (PMID 31772683, 2019).
leukemia (continued). "It is also well known that cytokine TNFα can regulate the robust activation of master transcription factor NF-κB, and persistent NF-κB overexpression/phosphorylation has been detected in leukemia as well as multiple myeloma." (PMID 31466313, 2019). "Several pro-inflammatory cytokines such as tumor necrosis factor-α and interleukin-1 elevated significantly in leukemia, we presumed that these elevated cytokines may be associated with nonspecific lesions." (PMID 31393345, 2019). "Within the positive therapeutic potential compounds, N-hydroxycinnamoylphenalkylamides (36H) are reported to have an inhibitory effect on the expression of matrix metalloproteinases- (MMP-) 9 in THP-1, a human leukemia monocytic cell line, which is stimulated by tumor necrosis factor-α (TNF-α)." (PMID 29507652, 2018). "Herein, we showed that IL-32 has a role in stromal cell crosstalk with leukemia cells, and that TNF-α must be part of this network, at least in vitro, since the protection from AraC-induced apoptosis conferred by HS5 miIL32 was reversed upon the addition of TNF-α." (PMID 28084439, 2017). "Also, exogenous HMGB1 positively correlated with the clinical status in childhood leukemia and stimulated leukemic cells to secrete TNF-α." (PMID 28404891, 2017). "In patients who are not infected with HIV, the disease may occur if they have underlying immunosuppressive conditions, such as Cushing's syndrome, sarcoidosis, hematological malignancies (leukemia or lymphomas), receipt of TNF inhibitors, or organ transplant." (PMID 27957359, 2016). "Importantly, additional administration of etanercept reversed the in vivo effect of BV6 single treatment on leukemia-free survival, indicating TNF-α dependency also in vivo." (PMID 26775704, 2016). "NF-κB is a key transcription factor involved in production of TNF-α in leukemia." (PMID 26516703, 2015). "As expected, TNFα treatment also strongly increased RARα expression, which may account, at least in part, for TNFα-induced differentiation in some leukemia cells." (PMID 25886043, 2015). "The non-specific inhibitor of SKs dimethylsphingosine (DMS) has been shown to inhibit leukaemia, colon, epidermoid, and lung tumour cell growth and to reduce metastasis in vivo, as well as increase the sensitivity of human leukaemia cells to apoptosis in response to radiation, TNF-α and Fas ligands." (PMID 24625663, 2014). "It is reported that arecoline stimulation increases TNF-alpha production in leukemia culture cells." (PMID 25200553, 2014). "However, addition of KG-1 cells or TNF-α to culture significantly increased E-selectin expression demonstrating that primary ECs can be activated by leukemia cells." (PMID 23560111, 2013). "In fact, NK cell reactivity against 4-1BBL-positive leukemia cells could be restored by neutralization of IL-10 or TNF-α (with Infliximab)." (PMID 23316193, 2012). "GITRL signaling into various leukemia cells induced the production of TNF-α, IL-6, and IL-8, or IL-10 that not only enhanced proliferation and survival of leukemia cells but also could suppress the immune system." (PMID 23316193, 2012). "We investigated the influence of 2-chlorodeoxyadenosine (2-CdA) in combination with tumour necrosis factor-α (TNFα) or its mutein VI, which differs from the native molecule by N-terminal amino acid composition, on the survival time of mice inoculated with leukaemia L1210 or P388." (PMID 18475640, 1995). "Therefore, while DNTs relied on IFNγ and TNFα to promote the anti-leukemic activity of Tconv cells, they may also promote recruitment of Tconv cells to the site of leukemia engraftment in vivo via the release of chemokines." (PMID 39876025, 2025). "High values of some systemic inflammatory cytokines (IL-6, IL-8, and TNF-α) in children with leukemia before the initiation of chemotherapy have been reported, and the authors concluded that elevated concentrations of inflammatory biomarkers could be a risk contributor for oral mucositis." (PMID 41149097, 2025).
leukemia (continued). "However, TNF-α inhibits disease progression by inducing apoptosis in leukaemia cells." (PMID 41235219, 2025). "Notably, the lower mean TGF-β levels in the AG and AA genotypes compared to GG suggest a potential impact of the TNFα − 308 G/A polymorphism on TGF-β regulation in the context of ALL, emphasizing the relevance of this genetic variant in leukemia pathophysiology." (PMID 39658797, 2024). "The data from the current study provide partial but important evidence that polymorphisms in apoptotic genes Bcl-2-938C>A and Bax-248G>A and pro-inflammatory cytokines IL-8 rs4073 T>A and TNF-α rs1800629 G>A may help predict the clinical outcomes of patients with leukemia." (PMID 37232720, 2023). "Finally, we found a statistically significant difference in the frequencies of TNF-α rs1800629 GG, GA, and AA genotypes between leukaemia patients and healthy controls (p = 0.048), with the AA and GG homozygote being more common among patients (7.96% and 83.18%, respectively)." (PMID 37232720, 2023). "While they have shown good effects against specific solid tumors and leukemias as mono-therapeutics, they can also sensitize cells to death in combined therapeutic regimens, as seen with temozolomide, cytarabine, prednisolone and even the pro-inflammatory cytokine TNF-α, in a variety of cell types." (PMID 34753495, 2021). "Therefore, we examined TNF-α expression changes in leukemia." (PMID 30934014, 2019). "Most notably, leukemia cells in patient 3 showed elevated expression of TNFSF12, which codes for a proinflammatory cytokine in the tumor necrosis factor (TNF) family called TWEAK, or TNF-like Weak Inducer of Apoptosis (also known as APO3L, CD255)." (PMID 39975227, 2025). "Most notably, leukemia cells in patient 3 showed elevated expression of TNFSF12, which codes for a pro-inflammatory cytokine in the tumor necrosis factor (TNF) family called TWEAK, or TNF-like Weak Inducer of Apoptosis (also known as APO3L and CD255)." (PMID 40632867, 2025). "In this study, seven cytokines (IL1β, IL4, IL6, IL8, GM-CSF, TNFα, and VEGF) were measured in neonatal blood spots from 1,020 ALL cases and 1,003 controls in the California Childhood Leukemia Study." (PMID 39658797, 2024). "The interplay between TNF-α and TGF-β in ALL underscores the complex role of cytokine signaling in leukemia." (PMID 39658797, 2024). "In fact, TNF-α Abs bind both soluble (s) TNF-α and transmembrane TNF-α, and so the targeted binding of Abs to leukemia cells is largely neutralized by sTNF-α." (PMID 39796700, 2024). "CML red pulp macrophages (RPMs) are able to produce a variety of cytokines and chemokines such as IL-10, CCL3, CCL4, CCL5, CXCL1, TNF-α, and SCF, to sustain leukemia initial cells (LICs)." (PMID 38779660, 2024). "Downregulation of HIF1α, oxidative phosphorylation, and PI3kinase pathways at EOI along with the regulators IFNG, TNF, VEGFA, IL1B in B cells is likely to impede leukemia supportive pro-inflammatory signaling." (PMID 37532715, 2023). "In human differentiated THP-1 cells (a human leukemia monocytic cell line), knockdown of PGAM5 stimulated TNFα and IL-6 secretion in naïve macropahges and increased TNFα, IL-6 and IL-1β in macropahges treated with IL-4 and IL-13 (M2 macrophage)." (PMID 37605246, 2023). "A previous study using a 42-plex human cytokine array to analyze the serum of NSG mice engrafted with Nalm6-GFP leukemia cells reported high levels of PDX-intrinsic PDGF-AA and FLT-3 L as well as lower levels of FGF-2, VEGF-A, and TNFα." (PMID 36860657, 2023). "IL-10 (interleukin-10) and TNF-α as well as TGF-β (transforming growth factor β) and IFN-γ are assumed to have contrary effects in anti-leukemia immunity." (PMID 37610672, 2023). "Constitutive NF-κB signaling activation and higher TNF-α secretion have been detected in AML, and its aberrant activity is involved in leukemia cells escaping apoptosis and accelerating proliferation." (PMID 35806401, 2022).